STAT5A (signal transducer and activator of transcription 5A)
Diseases named in the same sentence as STAT5A in open-access papers (continued):
Sharing a sentence is not in itself a finding about the gene and the disease.
tumor (continued). "Finally, this study showed that increased miR‐23a negatively regulated STAT5A, which further activated AKT signaling to enable rapid metabolism for accelerated tumor growth in HCC." (PMID 33155364, 2021). "Interestingly, restoration of STAT5A and IL2RG expression has been reported to impair NPM/ALK expression in ALCL cells, thus acting as tumor suppressors in this context." (PMID 34503232, 2021). "Furthermore, STAT5A subsequently induced AKT phosphorylation, which resulted in enhanced tumor glucose metabolism and tumor growth in HCC." (PMID 33155364, 2021). "Moreover, CD163 expression was positively correlated with most gene markers of these tumor-infiltrating immune cells in both the TCGA and CGGA cohorts, including CD8A, CD8B, STAT6, STAT5A, and PDCD1." (PMID 34395626, 2021). "The expression of STAT5a, p-STAT5a and ABCB1 detected by IHC was significantly decreased in tumor tissues from the pimozide group and combination group but did not vary between the DOX group and PBS group, suggesting the potent effect of pimozide on suppressing STAT5a and downstream ABCB1." (PMID 34336684, 2021). "Overexpression of transforming growth factor-α (TGFα), which enhances epidermal growth factor receptor (EGFR) activation, promoted the development of hyperplasia and tumours about one and a half months earlier in STAT5-expressing mice compared to STAT5a KO mice." (PMID 32872372, 2020). "Moreover, VC therapy did not exert a significant impact on tumor vessel coverage by pericytes, intratumoral hypoxia levels, and CD8+ T cell infiltration in these tumors with Tet2 or Stat5a deficiency." (PMID 38177099, 2024). "Consequently, we could conclude that the higher expression of STAT3, STAT4, STAT5A, STAT5B, and STAT6, the higher differentiation degree and less tumor stemness characteristics of BRCA tumor cells." (PMID 36968603, 2023). "Additionally, the 6 markers (KDR, CXCR6, STAT5A, MPL, NFATC3, and TLR6) we found to be downregulated in our late-recurring tumor samples are also biologically relevant to functional T-cell activity, which helps explain their expression and function in this context." (PMID 36195959, 2022). "This is suggestive of negative influence of STAT5A-NMI axis on tumor progression." (PMID 34078871, 2021). "The transcription factor, STAT5a/b, which is immediately downstream of EGFR Y845, also showed a significant decrease in phosphorylation at tyrosine positions 694 and 699 in both adjacent normal (P = 0.004) and tumor (P = 0.01) tissue samples from Anthos-treated animals." (PMID 34926717, 2021). "In head and neck cancer, STAT5b, but not STAT5a, was shown to be essential for tumour growth." (PMID 32899142, 2020). "Then, UBC modulated STAT5A and HSF1 in the WNT and the MAPK signaling pathways to inhibit DNA repair through the mediation of HIST2H2BE and to induce antiapoptosis through the mediation of HSPB1, which might finally facilitate tumor growth." (PMID 30344796, 2018). "However, comparison of the tumor-adjacent gastric tissue between HP+ and HP- patients revealed 8 differentially methylated CpG sites located within 7 genes (CCNA1, CSPG2, DAB2IP, DIO3, FLT1, STAT5A and TWIST1)." (PMID 24674026, 2014). "Then, UBC could modulate STAT5A and CEBPA in the WNT and the MAPK signaling pathways to inhibit DNA repair through the dysregulation of HIST2H2BE and to induce the accumulation of autoimmune defects through the dysregulation of IGF2, which might ultimately facilitate tumor growth." (PMID 30344796, 2018). "These complementary findings emphasize that STAT5A and STAT5B, despite high sequence homology, exert non-redundant biological effects on tumor behavior and patient prognosis." (PMID 41301421, 2025). "Studies indicated that STAT5A, but not STAT5B, is epigenetically silenced in NPM-ALK tumors and behaves as a tumor suppressor when reactivated to suppress NPM-ALK expression." (PMID 31963765, 2020).
tumor (continued). "Anterior and dorsal prostate lobes displayed the highest Stat5a/b deletion efficiency with no overt compensatory activation of other PRLR signaling cascade at 6 months of age; hence the development of tumor hallmarks was markedly reduced." (PMID 31269779, 2019). "EGFR was thus activated in DFSP infiltrative periphery and DFSP-T, and EGFR signaling in DFSP tumor progression preferentially involved TOR and STAT5a/b downstream effectors, but not ERK in the MAPK pathway." (PMID 29492209, 2018). "However, our data of Western blot showed that the phosphorylation of GSK-3β and STAT5a had no significant changes after ESCCAL_1 knockdown, suggesting that down-regulation of ESCCAL_1 inhibiting ESCC tumor growth involved in other signaling pathway." (PMID 29416654, 2018).
cancer (106 papers, 2007 to 2025). A tumor composed of atypical neoplastic, often pleomorphic cells that invade other tissues. "Here, we conducted a systematic meta-analysis of STAT5B to evaluate its association with overall survival across cancers and to compare its prognostic role with that of STAT5A." (PMID 41301421, 2025). "Here, we studied the most frequent and clinically challenging STAT5BN642H driver in T cell development and immature T cell cancer onset and compared it with STAT5A hyperactive variants in transgenic mice." (PMID 38618957, 2024). "Analyzing the gene alteration frequency and mutation types of STAT5a across cancer types using cBioPortal, we found less than 10% alteration frequency across 44 cancer types with a variation in mutation types." (PMID 37369132, 2023). "To investigate the potential role of STAT5a as a prognostic marker, we investigated the association between high STAT5a expression and overall survival in cancer patients." (PMID 37369132, 2023). "Mutation of STAT5A is frequently observed in cancers and GM-CSF is known to aggravate the disease through induction of PD-L1 expression." (PMID 35865534, 2022). "The recent discovery of STAT5A/B mutations in cancers and functional studies indicated that STAT5A/B mutants are oncogenic." (PMID 34148062, 2021). "To confirm these functional predicted effects observed with expression of these STAT5a mutants, we next assessed the loss of the STAT5a phospho-sites on cancer characteristics in vitro." (PMID 34188118, 2021). "Of particular interest is the association of STAT5A dysregulation with head and neck squamous carcinoma, which is a type of cancer that can be caused by high-risk HPV infection." (PMID 32641122, 2020). "Corroborating earlier work, high levels of nuclear Stat5a/b predicted increased risk of early cancer recurrence following radical prostatectomy in PCs of intermediate grade." (PMID 27741508, 2017). "Active Stat5a/b expression levels carry prognostic value by identifying patients at risk for cancer recurrence and poor clinical outcomes." (PMID 27741508, 2017). "Specific isoforms of STAT5A/B were associated with human cancer types, but the exact roles for each isoform in distinct cancer types are not studied yet." (PMID 25333255, 2014). "The aberrant expression and/or activities of several members of the STAT protein family, including STAT3 and STAT5A, have been implicated in the initiation, growth, and metastatic dissemination of various cancers, including head and neck, breast and brain cancers." (PMID 31783691, 2019). "Stat3 and Stat5a/b transcription factors have been implicated in several pathophysiological conditions, and pharmacological inhibition of both transcription factors has been proposed to treat certain diseases, such as malignancies." (PMID 31443474, 2019). "STAT5A, is a transcription factor mediating cellular responses to growth factors and promoting transcription of genes associated with proliferation, differentiation, and survival of cancer cells." (PMID 29416677, 2018). "In support of this concept, our data showed that the cancer-related activating mutations I699L and Q701L located in interface 2 of the STAT5A molecule indeed resulted in elevated dimerization levels, but remained highly susceptible to alteration of the F706 residue." (PMID 27752093, 2016). "To this end, we conducted a comprehensive meta-analysis of STAT5B expression and survival outcomes across a wide spectrum of cancers, employing the same rigorous bioinformatic pipeline previously applied to STAT5A." (PMID 41301421, 2025). "Compared with control cells, STAT5A-iMac showed increased killing activity and phagocytosis in both types of cancer cells." (PMID 39872864, 2024). "STAT5A affects cancer progression through multiple mechanisms, such as cell proliferation, differentiation, apoptosis, hematopoiesis, and immunity." (PMID 38879589, 2024).
cancer (continued). "Using the Kaplan–Meier plots from the Prognoscan analysis platform, we compared the overall survival between STAT5a high-expressing cancer patients and low-expressing cancer patients." (PMID 37369132, 2023). "Subgroup analysis was conducted to explore the possible differences in high STAT5a expression for overall survival in different cancers using HRs from the univariate analysis." (PMID 37369132, 2023). "We conducted analyses to compare STAT5a transcription levels in different cancer types to normal tissues to address this controversy." (PMID 37369132, 2023). "STAT proteins, particularly STAT1, STAT3, STAT5A and STAT5A, have been found to be hyperactivated in many cancers." (PMID 38255152, 2023). "In this study, we conducted a systematic analysis by pooling and extracting gene expression datasets to examine the gene expression pattern and the prognostic value of STAT5a across all cancer types." (PMID 37369132, 2023). "To address this controversy, we examined the prognostic role of STAT5a in cancer patients across multiple cancers." (PMID 37369132, 2023). "Future investigations looking at the effect of gene alterations of STAT5a are also needed to understand the role of STAT5a in various cancers." (PMID 37369132, 2023). "Phosphorylation of STAT5A significantly contributes to the transformation of cancer cells and inhibits apoptosis through up-regulation of the anti-apoptotic protein Bcl-xL." (PMID 38034788, 2023). "We inferred that LSECtin can also regulate STAT family members STAT1, STAT3, and STAT5A, which have been reported to be closely related with cancer." (PMID 35821222, 2022). "We also found cancer-specific alternative activation subpathways, such as the ones activating STAT5A in ErbB signaling pathway." (PMID 34039407, 2021). "The expression level of STAT5A was first quantitatively analyzed in a panel of human cancer-derived endothelial cells (CDECs) including breast and ovarian CDECs." (PMID 34650929, 2021). "In this study we performed RNA-sequencing of MCF7 cells expressing single-point phospho-deficient STAT5a mutants treated with PRL in attempts to identify differentially expressed genes and functional pathways for cancer outgrowth." (PMID 34188118, 2021). "Our future experiments also plan to further our knowledge on the paracrine influence of the stromal cancer compartment on epithelial STAT5a signaling by performing co-culture experiments of CAFs both in vitro and in vivo also." (PMID 32633727, 2020). "While several studies ascribe a pro-tumorigenic function of STAT5a in many cancers its role in human BCa remains somewhat mixed and controversial." (PMID 32633727, 2020). "Nevertheless, targeted disruption of STAT5A and STAT5B gives rise to distinct phenotypes in mice and only STAT5B has been reported to be a target of mutations in cancer." (PMID 30573779, 2019). "Deregulation of the Janus kinase/signal transducers and activators of transcription (JAK/STAT) signaling pathway is found in cancer with STAT5A/B controlling leukemic cell survival and disease progression." (PMID 30679796, 2019). "Mutations of upstream kinases, copy number gains, or activating mutations in STAT5A, or more frequently in STAT5B, cause altered hematopoiesis and cancer." (PMID 31690038, 2019). "Active Stat5a/b was found to be an independent prognostic marker of early cancer recurrence not only in high-grade PC but also in intermediate grade PC." (PMID 27741508, 2017). "We show that proliferation and death are promoted by two different transcriptional regulators of NOX5-L in cancer cells: STAT5A (unpublished data) and CREB, respectively." (PMID 26513170, 2015). "Supervised hierarchical analysis using ANOVA further revealed differential expression of several proteins implicated in cancer, including BRAF, STAT5A, and the Wnt pathway-related protein DVL3." (PMID 25999352, 2015).
cancer (continued). "The cancer-relevant transcription factors STAT5a and STAT5b are particularly challenging small-molecule targets because their SH2 domains are 93 % identical on the amino acid level." (PMID 25702814, 2015). "Activation of STAT5a and STAT5b occurs in a variety of cancers including both hematopoietic cancers and solid tumors, such as those of the breast, prostate, lung, head and neck, and brain." (PMID 19630967, 2009). "Differential expression or activity (or both) of STAT5a and STAT5b has been reported in other cancer model systems." (PMID 19630967, 2009). "Owing to their ability to regulate the expression of genes involved in cell-cycle regulation (cyclin D1, c-myc, and p21) and cellular survival (Bcl-XL), STAT5a and STAT5b have emerged as possible targets for cancer therapeutics." (PMID 17997837, 2007). "To clarify the prognostic significance of STAT5 isoforms, we previously performed a systematic meta-analysis of STAT5A across cancer types using publicly available microarray datasets, and in the present study, we extend this approach to STAT5B, enabling a direct comparison between the two isoforms." (PMID 41301421, 2025). "STAT3 and STAT5A/B can promote cancer development, whereas STAT1 is a cancer suppressor." (PMID 38318160, 2024). "These distinct findings suggest that STAT5A exhibits heterogeneity across different types of cancers, suggesting that m6A-modified STAT5A may interact with distinct reader proteins, thereby leading to diverse outcomes." (PMID 38879589, 2024). "Additionally, the overexpression of STAT5A was significant related to cancer proliferation and invasion." (PMID 38774752, 2024). "In addition, we found that STAT5A plays a more pivotal role in cancer progression and patient prognosis based on previous studies." (PMID 38879589, 2024). "We chose STAT5A/5B as there is a paucity of information on c-MYC-STAT5A/5B interaction in cancers." (PMID 39123391, 2024). "Thus, activation of the PAX6/STAT5A axis leads to a global downregulation of H4K20me3, triggers cancer cells lineage changing and confers a NE transcriptional profile in PCa cells." (PMID 38745318, 2024). "In addition, STAT5a has overlapping functions with STAT3 protein in cancer development and progression." (PMID 37369132, 2023). "Previous studies have indicated that STAT5a participates in cancer development and progression and could potentially be a therapeutic target in cancers." (PMID 37369132, 2023). "In addition, we used the Tumorscape database to analyze STAT5a amplifications and deletions across cancer types." (PMID 37369132, 2023). "Since previous studies investigated the relationship between activation of STAT5a and cancer development and progression, further investigations focusing on the relationship between STAT5a expression and cancer progression, and survival are needed to understand this relationship." (PMID 37369132, 2023). "Given these proteins’ relation to proper immune cell function and the importance of immunosenescence in cancer development, progression, and recurrence, the misregulation of STAT5A and MPL likely mediates increased oncogenesis in VS via their immune-related pathways." (PMID 36195959, 2022). "The link between activation of STAT5a and STAT5b to the progression of solid tumors in breast and prostate cancer, respectively, is clear but the mechanism behind the developments of these cancers requires further elucidation." (PMID 36755813, 2022). "Lastly, we determined whether mitochondrial STAT5A has any impact on cancer cell growth in vitro and in vivo." (PMID 34148062, 2021). "Genes including the HLA gene family, B2M, IRF4, and STAT5A might be the key genes involved in the anticolon cancer response of CD8+ T cells through the regulation of cholesterol metabolism." (PMID 34858500, 2021). "The role of STAT5a in hematopoietic neoplasms, especially in myeloid cell transformation, is broadly accepted, and STAT5a also promotes the development of several other cancers." (PMID 34336684, 2021).